PDE8A (phosphodiesterase 8A)
Description:
Hydrolyzes the second messenger cAMP, which is a key regulator of many important physiological processes. May be involved in maintaining basal levels of the cyclic nucleotide and/or in the cAMP regulation of germ cell development. Binding to RAF1 reduces RAF1 'Ser-259' inhibitory-phosphorylation and stimulates RAF1-dependent EGF-activated ERK-signaling. Protects against cell death induced by hydrogen peroxide and staurosporine.
Synonyms: HsT19550
Tractability: Small molecule: an approved drug acts on it; a structure with a bound ligand is known; a high-quality ligand is known; it has a binding pocket of medium quality; it belongs to a druggable protein family. PROTAC: ubiquitination databases record sites on it; a small molecule that binds it is known.
Target class: Phosphodiesterase 8A; Enzyme; Phosphodiesterase; Phosphodiesterase 8
Gene: Protein-coding gene on chromosome 15 (84,980,440 to 85,139,145, forward strand). Ensembl gene ENSG00000073417.
Subcellular location (Human Protein Atlas): Golgi apparatus
Pathways (Reactome):
Signal Transduction: G alpha (s) signalling events
Gene Ontology:
Molecular function: 3',5'-cyclic-AMP phosphodiesterase activity; 3',5'-cyclic-GMP phosphodiesterase activity; kinase binding; protein kinase activator activity; 3',5'-cyclic-nucleotide phosphodiesterase activity; phosphoric diester hydrolase activity
Biological process: cellular response to epidermal growth factor stimulus; positive regulation of ERK1 and ERK2 cascade; negative regulation of cAMP/PKA signal transduction; cAMP catabolic process; regulation of DNA-templated transcription; signal transduction
Cellular component: extracellular exosome; cytosol
Genetic constraint (gnomAD): Loss-of-function variants: 24 observed, 53.46 expected, observed/expected ratio (o/e) 0.45, 90% interval 0.32 to 0.63. The upper end of that interval is the gene's LOEUF score, 0.63, which puts it in group 2 of 6, group 1 being the genes least tolerant of losing a copy. Missense variants: 706 observed, 710.54 expected, observed/expected ratio (o/e) 0.99, 90% interval 0.93 to 1.06. Synonymous variants: 262 observed, 263.57 expected, observed/expected ratio (o/e) 0.99, 90% interval 0.9 to 1.1.
Homologues: Orthologues: chimpanzee PDE8A (99% identical), macaque PDE8A (98% identical), rabbit PDE8A (92% identical), pig PDE8A (91% identical), dog PDE8A (90% identical), guinea pig PDE8A (85% identical), mouse Pde8a (79% identical), rat Pde8a (79% identical), tropical clawed frog pde8a (75% identical), zebrafish pde8a (50% identical), Drosophila melanogaster Pde8 (37% identical), Caenorhabditis elegans pde-6 (29% identical), and 2 more. Paralogues in human: PDE8B (65% identical), PDE11A (19% identical), PDE4A (18% identical), PDE4D (18% identical), PDE4B (18% identical), PDE3B (18% identical), PDE3A (17% identical), PDE4C (17% identical), PDE2A (17% identical), PDE5A (17% identical), PDE1B (16% identical), PDE6C (16% identical), and 8 more.
Diseases named in the same sentence as PDE8A in open-access papers:
PDE8A is named in the same sentence as 31 diseases in open-access papers, as found by Europe PMC text mining. Sharing a sentence is not in itself a finding about the gene and the disease. The quoted sentences say what the papers report.
pancreatic cancer (15 papers, 2019 to 2022). "Therefore, circ-PDE8A is predicted to be a diagnostic indicator for cancer invasion evaluation and prognosis of pancreatic cancer." (PMID 33710802, 2021). "In addition, several ncRNAs such as AFAP1-AS1, UCA1, HOTAIR, PVT1, MALAT-1, circ-ADAM9, BC008363, circ-LDLRAD3, circ-IARS, circ-PDE8A, circ_0030235, and circ_0001649 have been associated with prognosis of pancreatic cancer." (PMID 34439315, 2021). "exosomal circ‐PDE8A derived from pancreatic cancer cells was found to be able to enter the blood circulation and was related to the progression and prognosis of pancreatic cancer." (PMID 35446993, 2022). "CircRNA PDE8A in sEVs can promote the occurrence and development of pancreatic cancer through Mir-338 /MACC1/MET pathway, which has a significant role in the progression of pancreatic cancer and can be as a potential biomarker." (PMID 34980146, 2022). "For example, exosomal circRNA PDE8A released by tumor facilitated invasive growth of pancreatic cancer." (PMID 35333693, 2022). "Tumor-released exosomal circ-PDE8A enhanced cell invasion in pancreatic cancer, and exosomal circ-PDE8A was a potential marker for cancer diagnosis or progression." (PMID 34530825, 2021). "Studies found that high level of circ-IARS or circ-PDE8A in plasma exosomes secreted by pancreatic cancer indicated a poor overall survival of patients with pancreatic cancer." (PMID 34439315, 2021). "For instance, we have illustrated that exo-circ-PDE8A plays a significant role in the malignancy of pancreatic cancer." (PMID 30925885, 2019). "Researchers have discovered that the expression level of circ-PDE8A in the blood was much higher in the pancreatic cancer model than in the NC group." (PMID 30925885, 2019). "In addition, the role of exosomes circRNA circ‐PDE8A in regulating the invasion of pancreatic cancer through the miR‐338/MACC1/MET pathway has also been described." (PMID 35446993, 2022). "Tumor-released exosomal circRNA PDE8A promotes invasive growth via the miR-338/MACC1/MET pathway in pancreatic cancer, which may be involved in the remodeling of the extracellular matrix." (PMID 35114891, 2022). "Exosomal circRNA PDE8A promotes pancreatic cancer invasion via the miR-338/MACC1/MET pathway." (PMID 33867829, 2021). "Additionally, the dysregulation of circ-PDE8A in exosomes has been found to contribute to the invasive growth of pancreatic cancer through the MACC/MET/ERK/Akt signaling pathway." (PMID 34486489, 2021). "Exosomal-PDE8A induces cell development via the miR-338/MACC1/MET pathway in pancreatic cancer." (PMID 33109773, 2020). "Additionally, circulating exosomal circRNAs PDE8A (circ‐PDE8A) derived from PDAC patients' plasma exosomes was also abnormally overexpressed in pancreatic cancer patients; and its levels were closely related to the tumor invasion, clinicopathological characteristics, and survival of PDAC patients." (PMID 32419229, 2020). "Therefore, circ-PDE8A and Circ-IARS may be useful biomarkers for pancreatic cancer detection, circ-LDLRAD3 might be applied in the diagnosis and prognosis of pancreatic cancer." (PMID 33816529, 2021).
pancreatic ductal adenocarcinoma (7 papers, 2021 to 2024). An infiltrating adenocarcinoma that arises from the epithelial cells of the pancreas. "Circulating tumor-secreted circ-PDE8A can be secreted into the bloodstream via exosome transfer, and plasma exosomal circ-PDE8A is associated with tumor invasion and prognosis in patients with pancreatic ductal adenocarcinoma (PDAC)." (PMID 36338993, 2022). "In a study conducted on pancreatic ductal adenocarcinoma, Circ-PDE8A was found in exosomes secreted by tumor cells into the blood circulation." (PMID 38321530, 2024). "For example, the level of circ-PDE8A has been detected in the plasma exosomes from patients with pancreatic ductal adenocarcinoma (PDAC) and exosomal circ-PDE8A has been found to be related to the progression and prognosis in PDAC patients." (PMID 35898929, 2022). "Exosomal circ-PDE8A can be used in the prediction of prognosis of pancreatic ductal adenocarcinoma." (PMID 38321530, 2024). "Exosomal circ-PDE8A may be a useful marker of pancreatic ductal adenocarcinoma progression." (PMID 34957113, 2021). "circ-PDE8A expression was detected by microarray analysis from liver-metastatic pancreatic ductal adenocarcinoma (PDAC) tissues, and high circ-PDE8A expression was correlated with lymphatic invasion, TNM stage and a poor survival rate of PDAC patients." (PMID 34202482, 2021).
depression (6 papers, 2019 to 2024). "Indeed, a recent study reports characteristic PDE8A RNA editing patterns in the blood of depressed patients and suicide attempters with major depression, suggesting its diagnostic potential." (PMID 35327657, 2022). "The finding that PDE8A RNA editing translated from brain to blood strengthen the association between inflammation and depression, and could pave the way for predictive blood-based biomarkers to evaluate depressive symptoms." (PMID 33931591, 2021). "Similar to 5-HT2C, several editing sites were reported in PDE8A and differential representation of the corresponding edited transcripts was detected in depression and suicide, providing novel targets for further functional characterization." (PMID 35327657, 2022). "We report significant alterations of RNA editing of PDE8A in the blood of depressed patients and suicide attempters with major depression, for which the suicide attempt took place during the last month before sample collection." (PMID 33931591, 2021). "We have investigated alterations of PDE8A RNA editing in the blood of controls, depressed patients and suicide attempters with major depression and identified specific combinations to discriminate between these groups." (PMID 33931591, 2021). "Overall, we observed that the changes in editing rates of PDE8A isoforms measured in depression and/or suicide were very similar in blood and brain." (PMID 33931591, 2021). "Different studies have indicated the involvement of the 15q chromosomic locus containing PDE8A gene in major depressive disorder and recurrent depression." (PMID 31332697, 2019). "We report region-specific alterations of RNA editing of PDE8A in the cortex of suicides with major depression." (PMID 30770787, 2019). "There is a two-fold decrease in the expression of phosphodiesterase 8A (PDE8A) in the temporal cortex of major depressive disorder (MDD) patients." (PMID 30770787, 2019). "Measurement of expression levels of ADARs in the brain of major depressive disorder/suicide decedents and examination of both expression and editing in PDE8A would be interesting." (PMID 30770787, 2019). "We identified region-specific alterations of RNA editing of an immune response marker, PDE8A, in the cortex of suicide decedents with major depression." (PMID 30770787, 2019). "PDE8A was studied in terms of RNA editing alterations in depression and suicide." (PMID 35327657, 2022). "The observation of region-specific alterations of RNA editing of PDE8A in the cortex of suicide decedents with major depression raises the possibility of providing a marker for discriminating between suicides and control groups and suggests an immune response-related brain mechanism for suicide." (PMID 30770787, 2019). "Interestingly, the reported alterations of PDE8A RNA editing in the cortex of suicide decedents with major depression were observed in a genomic position, e.g., 15q25.3, which was reported to contain genes that contribute to susceptibility to major depression." (PMID 30770787, 2019). "Interestingly, editing efficiencies at sites B, C, and E in phosphodiesterase 8A (PDE8A), a key modulator of signal transduction downstream of 5-HT2C, were decreased in the brain and blood of patients with depression." (PMID 34681616, 2021). "PDE8A mRNA editing profiles in dorsolateral prefrontal cortex (BA9) and anterior cingulate cortex (BA24) differed and there were region-specific alterations of RNA editing of PDE8A in suicide decedents with major depression." (PMID 30770787, 2019). "RNA editing modifications were analyzed using a panel of eight genes (CAMK1D, GAB2, IFNAR1, KCNJ15, LYN, MDM2, PDE8A, PRKCB) that we previously identified and whose editing combinations were suggested as biomarkers to distinguish BD from unipolar depression and subcategories of BD patients." (PMID 39684694, 2024).
glioma (3 papers, 2020 to 2024). A benign or malignant brain and spinal cord tumor that arises from glial cells (astrocytes, oligodendrocytes, ependymal cells). "Additionally, the structural and functional similarities between PDE8B and another family member, PDE8A, which has been found to regulate stemness in glioma-initiating cells and exhibit tumor-suppressive properties, further complicate the understanding of their roles in cancer." (PMID 38989284, 2024). "However, Wang H reported that upregulated expression of miR-33a was correlated with poor prognosis of GBM patients and enhanced self-renewal of glioma-initiating cells via activation of the PKA and NOTCH pathways by targeting PDE8A and UVRAG." (PMID 32206036, 2020).
systemic lupus erythematosus (3 papers, 2019 to 2022). An autoimmune multi-organ disease typically associated with vasculopathy and autoantibody production. "Orlowski and colleagues used traditional cloning-sequencing approach to detect RNA editing in PDE8A transcripts in T cells of control and systemic lupus erythematosus patients." (PMID 30770787, 2019).
breast carcinoma (2 papers, 2021 to 2026). "For example, in breast cancer cells, PDE8A forms a complex with Raf-1 at the plasma membrane, generating a local microdomain with reduced cAMP levels." (PMID 41601682, 2026). "Although a wide range of PDE genes were seen to be expressed in some of these breast cancers by these methods, the PDE8A gene was prominently expressed at the mRNA level in all the breast cancer cells as well as all the breast cancer tissues examined." (PMID 33937235, 2021). "It was shown that PDE8A plays a major role in controlling T cell and breast cancer cell motility, including adhesion to endothelial cells under physiological shear stress and chemotaxis." (PMID 33937235, 2021). "It was shown that PDE8A regulates motility of lymphocytes and breast cancer cells, including adhesion to endothelial cells under physiological shear stress and chemotaxis." (PMID 33937235, 2021). "Therefore, consistent with our observation of PDE8A being important in the regulation of lymphocyte chemotaxis, it may also be an important regulator, and thus an important target for control of breast cancer cell migration as well." (PMID 33937235, 2021). "Conversely, pharmacological inhibition of PDE8A restores cAMP/PKA-dependent suppression of Raf-1, diminishes Integrin α L function, and thereby reduces adhesion and metastasis in breast cancer cells." (PMID 41601682, 2026). "In addition to its prominent expression in breast cancer cells, expression of PDE8A in the form of an AKAP13-PDE8A fusion transcript has been reported to be highly recurrent in colon cancer cells as well." (PMID 33937235, 2021).
melanoma (2 papers, 2019 to 2024). A malignant, usually aggressive tumor composed of atypical, neoplastic melanocytes. "PPL-008 was efficacious in the attenuation of ERK signalling in both cases and suggests that the PDE8A – C-Raf complex is a promising therapeutic target for B-Raf inhibitor resistant melanoma." (PMID 30909892, 2019). "We have used a novel cell-penetrating peptide agent (PPL-008) that inhibits the PDE8A – C-Raf complex in a human malignant MM415 melanoma cell line and MM415 melanoma xenograft mouse model to investigate ERK MAP kinase signalling." (PMID 30909892, 2019). "Indeed, inhibiting PDE8A in melanoma has been shown to suppress the MAPK pathway and tumor growth, hinting at an oncogenic role for PDE8A." (PMID 38989284, 2024). "We report data from the testing of our novel PDE8A – C-Raf disrupter/HOXD12 conjugate (from here on, named PPL-008) in MM415, a B-Raf inhibitor resistant malignant melanoma cell line (MM415; BRAF wt, KRAS wt, NRAS Q61L) and in an MM415 melanoma murine xenograft model." (PMID 30909892, 2019).
adrenal tumor (1 paper, 2020). "Transcriptome profiling of pediatric ACTs (n = 16) and normal adrenal cortex samples (n = 6) revealed that PDE2A, PDE6D, PDE8A, and PDE9A are highly expressed in both normal and adrenal tumor tissue, compared to other PDE family members." (PMID 32098292, 2020).
adrenocortical tumors (1 paper, 2020). "In the present work, when the transcriptome analysis was accessed, a decrease of PDE2A, PDE5A, and PDE8A expression and a significant overexpression of PDE4B and PDE8B was observed in adrenocortical tumors, compared to normal adrenal tissue." (PMID 32098292, 2020).
cardiac arrhythmia (1 paper, 2021). Any disturbances of the normal rhythmic beating of the heart or MYOCARDIAL CONTRACTION. "Studies in isolated ventricular myocytes from Pde8a knockout hearts have demonstrated that this enzyme regulates Ca2+ signaling during β-adrenergic stimulation, suggesting that it could protect against cardiac arrhythmias." (PMID 33807511, 2021).
Cognitive impairment (1 paper, 2024). Abnormal cognition is characterized by deficits in thinking, reasoning, or remembering. "Memory and cognitive impairments are common in SZ, further linking PDE8A to these psychiatric conditions." (PMID 39684694, 2024).
Globozoospermia (1 paper, 2022). Any structural anomaly of the acrosome resulting in a round sperm head. "It would be interesting to identify mutation on PDE8A gene related to patients affected by globozoospermia or other infertility defects." (PMID 36277728, 2022).
HIV-1 infection (1 paper, 2014). The type species of lentivirus and the etiologic agent of acquired immunodeficiency syndrome (AIDS). "We analyzed whether differential expression of PDE8A during cytokine activation of macrophages may contribute to the decreased susceptibility of these cells to HIV-1 infection." (PMID 25295610, 2014).
Leydig cell tumor (1 paper, 2022). A sex cord-stromal tumor occurring in the testis and rarely in the ovary. "Interestingly, we found that the expression of PDE8B but not of PDE8A is increased in transformed Leydig cells (Leydig cell tumors-LCTs) compared to non-tumoral cells." (PMID 36277728, 2022).
lupus erythematosus (1 paper, 2019). An autoimmune, connective tissue chronic inflammatory disorder affecting the skin, joints, kidneys, lungs, heart, and the peripheral blood cells. "A-I RNA editing activity on the phosphodiesterase 8A (PDE8A) gene, a previously identified RNA editing hotspot in the context of lupus erythematosus, was quantified by using an ultra-deep next-generation sequencing approach." (PMID 31332697, 2019).
neuroblastoma (1 paper, 2019). Neuroblastoma (NB) is the most common solid, extracranial childhood tumor. "In sum, while we confirmed IFN-dependent A-to-I editing on the PDE8A B gene, we further comprehensively described the RNA editing events that occur on intron 9 of the PDE8A gene in the human neuroblastoma cell line." (PMID 31332697, 2019).
osteoporosis (1 paper, 2025). A condition of reduced bone mass, with decreased cortical thickness and a decrease in the number and size of the trabeculae of cancellous bone (but normal chemical composition), resulting in increased fracture incidence. "Additionally, the mRNA relative expression of CIR1, GPR27, and PDE8A were reduced in the osteoporosis group, while NIF3L1 and VPS35 were increased." (PMID 40980812, 2025).